TSC2 (TSC complex subunit 2)
Diseases named in the same sentence as TSC2 in open-access papers (continued):
Sharing a sentence is not in itself a finding about the gene and the disease.
hamartoma (continued). "The activation of the mTOR pathway due to genetic alterations of the tuberous sclerosis complex in the TSC1 or TSC2 genes in hamartomas has also been reported as well as the subsequent therapeutic implications." (PMID 38622693, 2024). "TSC2, the tuberous sclerosis complex, the most common gene for an autosomal dominant genetic disease, is featured by the formation of benign tumors (hamartomas) in different organs." (PMID 36422197, 2022). "Mutations on either of the two genes Tuberous Sclerosis Complex 1 (TSC1) or Tuberous Sclerosis Complex 2 (TSC2) play a role and result in hamartomas involving many organs, like the brain, heart, kidneys, skin, lungs, and liver." (PMID 33552794, 2021). "Tuberous sclerosis complex (TSC) is an autosomal dominant disorder characterized by hamartomas in multiple organs associated with germline mutations in TSC1 and TSC2, including exonic, intronic, or mosaic mutations." (PMID 34465349, 2021). "It is thought that tuber/hamartoma development requires “two hits,” whereby a germline mutation in one allele of TSC1 or TSC2 is complemented by a second somatic mutation in the other allele, leading to cell growth derangement and hamartoma formation." (PMID 28367137, 2017). "TSC occurs due to inactivating mutations in either of two genes, TSC1 in chromosome 9q34 or TSC2 in chromosome 16p13, and follows the two hit tumor suppressor model of pathogenesis in most hamartomas." (PMID 28968464, 2017). "We discovered that roughly two-thirds of hamartomas from TSC1/TSC2 patients harboured two TSC hits, including most RAs and SEN/SEGAs, while second hits were found in only 35% of cortical tubers." (PMID 28643795, 2017). "Disruption in the TSC1/TSC2 complex leads to constitutive activation of mTORC1, resulting in unchecked protein synthesis, cell cycle progression, and ultimately the development of benign tumors, or hamartomas, characteristic of TSC." (PMID 40722560, 2025). "Furthermore, loss of heterozygosity (LOH) of TSC1 or TSC2 has been reported in approximately 80% of SEGAs and has also been found in other TSC hamartomas." (PMID 34709498, 2022). "Certainly the study of benign diseases has led to unexpected discoveries and insights relevant to malignant cancers, for example, in studying hamartomas associated with Cowden's and Tuberulo Sclerosis syndromes and the identification of PTEN and TSC2 genes, respectively." (PMID 23785396, 2013). "While the two-hit hypothesis is the prevailing model, not all TSC-associated hamartomas have been found to contain dual inactivating variants in TSC1/TSC2." (PMID 38540392, 2024). "In the tumor model of mice with heterozygous mutations in TSC2 (Tsc2+/- ) there was no reduction in tumor size after metformin treatment compared with those treated with rapamycin, suggesting limited therapeutic benefits of metformin in treating hamartomas." (PMID 33821877, 2021). "Mutations in TSC1 or TSC2 gene cause tuberous sclerosis complex (TSC), an autosomal dominant disorder characterized by the formation of non-malignant hamartomas in multiple vital organs." (PMID 31655562, 2019). "mTORC1 is constitutively activated in cells lacking either TSC1 or TSC2 and in hamartomas from TSC patients." (PMID 22363765, 2012). "The distribution of cells expressing phospho-S6 and phospho-Erk in mice injected with TSC2-/meth cells resembles what we observed in fibromas isolated from TSC patients, where these proteins are mainly expressed in the subcutaneous, as previously reported for human TSC hamartomas." (PMID 36077111, 2022).
hamartoma (continued). "This has led to speculation that treatment of TSC hamartomas with mTORC1 inhibitors might lead to restoration of AKT activation, as seen in vitro with treatment of TSC1/TSC2 null cells, and in some patients with malignant disease, which may compromise clinical benefit." (PMID 19527517, 2009). "We conclude that neither bortezomib nor metformin has significant benefit in this native Tsc2+/− mouse model, which suggests limited benefit of these compounds in the treatment of TSC hamartomas and related lesions." (PMID 22363765, 2012).
PEComas (42 papers, 2011 to 2026). "Unfortunately, mTOR inhibitors do not appear to improve PFS relative to standard chemotherapy regimens or provide OS benefit in TSC1/TSC2 mutated malignant PEComas." (PMID 40900800, 2025). "PEComas frequently contain TSC1 or TSC2 mutations, leading to aberrant activation of the mTOR pathway." (PMID 41463261, 2025). "Dysregulation of the mTOR signaling due to functional mutations or loss of TSC1 or TSC2 leads to abnormal cell growth and the development of PEComas." (PMID 39220642, 2024). "Loss of heterozygosity in the TSC2 locus, such as deletion of 16p or TSC2 mutations, resulting in loss of function of the tuberin protein are commonly found in PEComas." (PMID 37041531, 2023). "Although most PEComas harbor loss-of-function TSC1/TSC2 mutations, a small subset of PEComas show rearrangement of the TFE3 gene." (PMID 36647157, 2023). "The majority of PEComas show genetic alterations in TSC2 (the result of a loss of heterozygosity in the TSC2 gene) and, less commonly, TSC1." (PMID 36647137, 2023). "PEComas often harbor somatic inactivating mutations in either TSC2 or TSC1, and patients with tuberous sclerosis complex, who carry germline mutations in these genes, often develop various types of PEComas during their lifetime." (PMID 37448552, 2023). "Like TSC, the TSC2 locus frequently undergoes somatic loss-of-heterozygosity (LOH) mutations in perivascular epithelial cell tumors (PEComas)." (PMID 35483879, 2022). "The majority of PEComas have a loss of function (LOF) of TSC-1 or -2 genes (commonly TSC-2 LOF), leading to increased mTOR pathway activation." (PMID 36360169, 2022). "The activation of the mTOR pathway through the loss of the tuberous sclerosis complex 1 (TSC1)/TSC2 repressor complex seems to be a common pathogenic event in PEComas." (PMID 34542724, 2021). "A subset of malignant PEComas are associated with mutations (inactivation or deletions) of TSC1 or TSC2, negative regulators of the mTOR signaling pathway." (PMID 34637337, 2021). "Inhibition of hyperactivated mTORC1, which results from loss of the TSC1/TSC2 tumor suppressor complex, is a specific molecular target for PEComas therapy." (PMID 34442003, 2021). "Generally, in conventional advanced PEComas pathologically activated by the loss of the TSC1/TSC2 tumor suppressor complex, mTOR1 is a rational mechanistic target for the therapy with its inhibitors, such as rapamycin or everolimus." (PMID 31103952, 2019). "Taken together, these observations suggest that activation of mTOR through loss of the TSC1/TSC2 repressor complex, or potentially by other means, is likely a common and critically pathogenic event in PEComas." (PMID 22943457, 2012). "PEComas are associated with mutations or deletions of tuberous sclerosis associated genes TSC1 or TSC2, which act as tumor suppressor genes by regulating mTOR." (PMID 21846376, 2011). "Therefore, the immunoprofile of renal and extrarenal TFE3-rearranged PEComas overlaps, but it slightly differs from PEComas related to TSC1/TSC2 mutations, in which the expression of muscle markers, particularly actin, is more frequently observed." (PMID 39410016, 2024). "The most common genetic alteration present in sporadic or hereditary PEComas is a loss of function of the TSC1 (~ 27%) or TSC2 (~ 73%) genes, leading to the activation of mTOR signaling, which may represent a therapeutic target." (PMID 38243242, 2024). "In humans, PEComas generally have mutations in the TSC1/TSC2 genes, but MiT/TFE translocations have been observed when those are absent, suggesting that the pathways may converge, which is consistent with our earlier pioneering studies." (PMID 38386415, 2024). "Therefore, the two-hit mutation of TSC1 or TSC2 is causally associated with the onset of TSC-PEComas." (PMID 35928867, 2022).
PEComas (continued). "PEComas are usually associated with TSC-2 and rarely TSC-1 loss-of-function mutations." (PMID 34918628, 2021). "Sporadic PEComas were also found to carry TSC1 or TSC2 somatic inactivating mutations." (PMID 34442003, 2021). "Molecularly, most PEComas are defined by a loss of function of the TSC1/TSC2 complex." (PMID 31309284, 2020). "Genetic studies have found that PEComa may occur as a sporadic disease or as a component of TSC (including TSC1 and TSC2), which suggests the oncogenesis of PEComas as a TSC-associated neoplasm." (PMID 31171030, 2019). "Furthermore, such PEComas lack TSC1/TSC2 inactivating mutations of conventional PEComas and retain their protein expression according to immunohistochemistry data." (PMID 31103952, 2019). "Also, TFE3 rearrangements have been found to be mutually exclusive with TSC2 mutations in PEComas which has been hypothesized to be responsible for the worse prognosis of these patients." (PMID 37448552, 2023). "Molecularly, PEComas often harbor TSC1/TSC2 gene alterations leading to the activation of the mTOR signaling pathway." (PMID 41479435, 2026). "Molecular alterations in uterine PEComas frequently involve dysregulation of the mTOR signaling pathway, most often due to inactivating mutations in the TSC1 or TSC2 genes." (PMID 41463261, 2025). "Molecular alterations in conventional PEComas often involve mutations, copy number losses, or rearrangements in the TSC1 or TSC2 genes, and they are reported in up to 90% of cases." (PMID 40647483, 2025). "Malignant perivascular epithelioid cell tumors (PEComas) are rare tumors in which the PI3K/AKT/mTOR pathway is critical for pathogenesis and is often associated with mutations in the TSC1/TSC2 genes." (PMID 40989692, 2025). "Two major molecular subgroups have recently been identified for PEComas: those with TSC1 or TSC2 alterations and those with TFE3 fusions." (PMID 37041531, 2023). "The most common genetic alterations in sporadic and hereditary PEComas demonstrate inactivation of the TSC2 (16p13.3) and the TSC1 (9q34) genes." (PMID 36367123, 2023). "In contrast to conventional PEComas, TFE3-rearranged PEComas were shown to lack TSC2 inactivating mutations." (PMID 37470853, 2023). "Perivascular epithelioid cell tumors (PEComas) are associated with mutations in TSC1 and TSC2 with subsequent activation of the mTOR pathway." (PMID 35626152, 2022). "Regarding molecular characteristics, PEComas are characterized by mutations leading to mTOR pathway activation, such as TSC1 or TSC2 bi-allelic inactivation, TFE3 gene fusion and FLCN truncating mutations." (PMID 34680376, 2021). "The important study by Kenerson revealed that PEComas usually show increased mTOR signaling, in most cases related to impairment of TSC2 function." (PMID 31309284, 2020). "PEComas are associated with genetic alterations similar to those in TSC, an autosomal dominant genetic disease caused by the loss of TSC1 (9q34) or TSC2 (16p13.3) genes." (PMID 31103952, 2019). "Actually, the genetic and molecular bases of PEComas appear to be aberrations on chromosome 16 and at the TSC2 locus resulting in activation of the mTOR pathway." (PMID 27871249, 2016). "Longer-term therapeutic responses with significantly improved efficacy over chemotherapy can be achieved with mTOR inhibitors in malignant PEcoma, especially in patients with mutations in the TSC1/TSC2 genes that result in aberrant activation of the mTOR pathway." (PMID 40989692, 2025). "Molecularly, most PEComas, harbor a loss of function of the TSC1/TSC2 complex." (PMID 38664269, 2024). "Although most patients have sporadic PEComas, a subset may be associated with the inactivation of TSC1 or TSC2 genes and the occurrence of TFE3 gene fusions." (PMID 36367123, 2023). "Moreover, in 10–20% of sporadic PEComas cases, loss of 9q34 (TSC1) or 16q13.3 (TSC2) has been reported." (PMID 34442003, 2021).
PEComas (continued). "Ninety-one percent (10 of 11) of PEComas with TSC1 or TSC2 mutations were pS6+, whereas only 44% (5 of 11) without TSC1 or TSC2 mutations were pS6+ (Fisher's exact P = .06)." (PMID 34637337, 2021). "PEComas can be related to genetic alterations of tuberous sclerosis complex [TSC], an autosomal dominant disease due to loss of TSC1 or TSC2 genes involved in the regulation of the Phosphatidylinositol 3-Kinases [PI3K]/AKT/Mammalian Target of Rapamycin [mTOR] signaling pathway." (PMID 32685651, 2020). "Most PEComas arise sporadically, but may be associated with tuberous sclerosis complex (TSC), an autosomal dominant genetic disorder that is caused by germline mutations in the TSC1 or TSC2 genes." (PMID 38243242, 2024). "Most PEComas arise sporadically, but may be associated with tuberous sclerosis complex (TSC), an autosomal dominant genetic disorder characterized by germline mutations in the TSC1 or TSC2 genes." (PMID 38243242, 2024). "Interestingly, the response rate was 89% in PEComas with a TSC2 mutation, whereas it was 13% without." (PMID 37041531, 2023). "Molecularly, most PEComas, including sporadic ones, are defined by a loss of function of the TSC1/TSC2 complex, in the majority of the cases the result of a loss of heterozygosity (LOH) in the TSC2 gene, leading to increased mTORC1 activation and deregulated cell growth signaling." (PMID 31309284, 2020). "PEComas are related to the genetic alterations of tuberous sclerosis complex (TSC), an autosomal dominant genetic disease associated with losses of TSC1 (9q34) or TSC2 (16p13.3) genes, which seem to have a role in the regulation of the Rheb/mTOR/p70S6K pathway." (PMID 24965209, 2014). "PEComas are most commonly found in females and often show either TSC1 or TSC2 alterations, which result in the activation of the mTOR pathway, or TFE3 fusions." (PMID 37041531, 2023). "Even though access to molecular biology has increased since previous reviews, very few cases reported the search for a TFE3 translocation, a TSC1 or TSC2 loss of function mutations or even no FCLN mutation, considered to be the more recent genomic alterations described in PEComas." (PMID 34680376, 2021). "However, patients with TFE3-rearranged PEComas, which do not involve the TSC2 gene, will likely fail to respond to mTOR1 inhibitors." (PMID 31103952, 2019). "Interestingly, these PEComas are characterized by the absence of more common mutations in the TSC1 and TSC2 genes, which also alter TFE3/TFEB regulation, upon which the pathogenesis may converge." (PMID 38386415, 2024). "Although most soft tissue PEComas are not related with TSC, many exhibit TSC2 changes." (PMID 39026968, 2024). "However, homozygous and/or heterozygous deletion of TSC1 or TSC2 generally does not induce the formation of renal AML in mice, although one previous mouse model of mosaic TSC1 deletion developed renal mesenchymal lesions that resembled human PEComas, with upregulated melanocytic marker expression." (PMID 41044182, 2025).
Intellectual disability (39 papers, 2014 to 2026). "Mutational variants identified in the TSC2 gene correlated with a more severe clinical presentation, including severe intellectual disability and treatment-resistant seizures, compared to variants in the TSC1 gene." (PMID 40364023, 2025). "Severe intellectual disability was also present in four patients, all of whom carried pathogenic TSC2 mutations, reinforcing existing data about genotype–phenotype correlations." (PMID 40364023, 2025). "Patients with TSC2 mutations had more severe seizures, were diagnosed 9–11 years earlier and were significantly more likely to have intellectual disabilities than those with TSC1 mutations." (PMID 41291828, 2025). "Patients with TSC2 variants usually present a higher number of tubers, an earlier age of seizure onset, and a higher prevalence of intellectual disability compared to those with TSC1 variants." (PMID 38439608, 2024). "The TSC2 c.250G>A p.(A84T) variant was identified in an individual with intellectual disability and a single hypomelanotic macule." (PMID 31799751, 2020). "However, evidence from the literature suggests that TSC2 mutations are associated with a higher proportion of severe phenotypes, developmental deficits, and intellectual disability than TSC1 mutations." (PMID 37946245, 2023). "There is a higher incidence of intellectual disability in patients with TSC2 mutations, and it has been suggested that severity of disability may correlate with predicted effects of mutations on Tsc1 and Tsc2 protein." (PMID 35883484, 2022). "However, another study revealed that only milder developmental delay and/or intellectual disability was observed in patients with TSC1 mutations than in those with TSC2." (PMID 33679864, 2020). "Children and those with TSC2 had significantly higher rates of intellectual disability, suggesting that age and genotype comparisons should be interpreted with caution." (PMID 30201051, 2018). "We did not observe gene expression differences between important subgroups, that is individuals with TSC2 versus TSC1 mutations, or mild versus severe intellectual disability." (PMID 28808237, 2017). "In particular, TSC2+/- mutant mice display reduced mGluR-LTD responses, which are associated with intellectual disabilities, and these symptoms can be improved by enhancing mGluR signaling." (PMID 24744698, 2014). "Tuberous sclerosis complex (TSC) is an inherited multisystem disorder, comprising both TSC1 and TSC2, and involves a range of symptoms including epilepsy, autism spectrum disorder (ASD), intellectual disability (ID) and slow growing hamartomas in many organs." (PMID 37880800, 2023). "Some studies have shown that the existence of TSC2 inactivation variants may affect the severity of TSC-related brain damage, and children with TSC2 protein truncation mutations are more likely to develop progressive cognitive deterioration and severe intellectual disability." (PMID 32655475, 2020). "Nonetheless, we note that both individuals with a mosaic TSC2 mutation had TSC with multiple organ involvement, but mild or no intellectual disability." (PMID 25927202, 2015). "Special attention should be paid to adults with mutations in TSC2 since they seem to be at a higher risk for newly occurring SEGA and SEGA growth in adulthood as well as to individuals with intellectual disability who might not be able to verbally express SEGA-related symptoms." (PMID 31428037, 2019). "Therefore, it is unknown what kind of TAND symptoms patients without intellectual disabilities have, and whether there are any differences between TSC1 and TSC2 patients." (PMID 36232477, 2022).